TYRO3 (TYRO3 protein tyrosine kinase)
Diseases named in the same sentence as TYRO3 in open-access papers (continued):
Sharing a sentence is not in itself a finding about the gene and the disease.
Ewing sarcoma (1 paper, 2024). A small round cell tumor that lacks morphologic, immunohistochemical, and electron microscopic evidence of neuroectodermal differentiation. "Here, using phospho-profiling, we find Ewing sarcoma cells treated with chemotherapeutic agents activate TAM (TYRO3, AXL, MERTK) kinases to augment Akt and ERK signaling facilitating chemoresistance." (PMID 38906855, 2024).
gastrointestinal carcinoma (1 paper, 2020). "Consistent with METHY analysis, a pan-gastrointestinal carcinoma cluster with COAD/READ-STAD was gathered in C2, which had high level of CDH1, CLDN7 and TYRO3, and a low level of CAV1." (PMID 32874774, 2020).
glomerular disease (1 paper, 2023). "Taken together, the in vivo data indicate that C-10 confers renoprotection in glomerular disease by specific agonism of TYRO3 in podocytes." (PMID 36454644, 2023). "In conclusion, we developed what we believe is a novel TYRO3-specific agonist (C-10), which was shown to attenuate proteinuria and podocyte injury in 2 animal models of glomerular disease." (PMID 36454644, 2023). "Among the 3 TAM receptors (TYRO3, AXL, and MER), only TYRO3 expression is largely restricted to podocytes, and glomerular TYRO3 mRNA expression negatively correlates with human glomerular disease progression." (PMID 36454644, 2023). "One major concern of using TYRO3 agonists to treat glomerular disease is its potential tumorigenesis and suppression of antitumor immunity." (PMID 36454644, 2023). "Our previous study showed that PS/TYRO3 signal transduction protects podocytes from injury in the settings of glomerular disease." (PMID 36454644, 2023). "Similar to PS knockout, we previously showed that TYRO3 aggravates podocyte injury, and conversely, the induction of TYRO3 in podocytes attenuates injury in animal models of glomerular disease." (PMID 36454644, 2023). "Therefore, as a potential therapeutic target in glomerular disease, we focused on the agonism of TYRO3." (PMID 36454644, 2023). "Our data further support the protective role of TYRO3 in podocytes and TYRO3 agonists could be a potential new therapy for glomerular disease." (PMID 36454644, 2023). "Importantly, similar to what was observed previously with PS/TYRO3 overexpression models, we confirmed that C-10 administration attenuated podocyte injury in vivo in 2 mouse models of glomerular diseases, ADRN as an FSGS model and a diabetic db/db model." (PMID 36454644, 2023). "As PS function is not limited to TYRO3-mediated signal transduction but includes its anticoagulant activity, we focused on the development of TYRO3 agonists as an optimal therapeutic approach to glomerular disease." (PMID 36454644, 2023). "Moreover, these renoprotective effects of C-10 were lost in Tyro3-knockout mice, indicating that C-10 is a selective agonist of TYRO3 activity that mitigates podocyte injury and glomerular disease." (PMID 36454644, 2023). "We will also assess whether the low dose of TYRO3 agonist (2.5 mg/kg/day) used for the treatment of glomerular disease will affect tumorigenesis in vitro and in vivo." (PMID 36454644, 2023). "The question to resolve in future studies is how we could avoid potential tumorigenesis while we treat glomerular disease with TYRO3 agonists." (PMID 36454644, 2023). "Therefore, C-10, a TYRO3 agonist, could be potentially developed as a new therapy for glomerular disease." (PMID 36454644, 2023). "Therefore, we posited that the agonistic PS/TYRO3 signaling could serve as a potential therapeutic approach to attenuate glomerular disease progression." (PMID 36454644, 2023). "However, independent of TYRO3 activation, PS plays a significant role in the anticoagulation system, and would not be an optimal target for the treatment of glomerular disease." (PMID 36454644, 2023).
Hepatitis (1 paper, 2022). Inflammation of the liver. "Tyro3 was reported to contribute significantly to tumor growth, aggressiveness and liver dysfunction in HCC and was also considered a marker and therapeutic target for HCC with a higher hepatitis activity." (PMID 36059952, 2022).
idiopathic pulmonary fibrosis (1 paper, 2024). Idiopathic pulmonary fibrosis (IPF) is a nonneoplastic pulmonary disease that is characterized by the formation of scar tissue within the lungs in the absence of any known cause. "In patients with Idiopathic Pulmonary Fibrosis (IPF), Gas6, Axl, and Tyro3 were elevated compared to the healthy control, and phosphorylated Axl was higher in rapid progressors versus slow progressors." (PMID 39057085, 2024).
male infertility (1 paper, 2015). The inability of the male to effect fertilization of an ovum after a specified period of unprotected intercourse. "Similarly, reduction in Tyro3 expression may contribute to male infertility and the response to retinal self antigen of Axl and Mertk double-knockout mice." (PMID 26656104, 2015).
myeloid leukemia (1 paper, 2022). A clonal proliferation of myeloid cells and their precursors in the bone marrow, peripheral blood, and spleen. "Knockdown of TYRO3 has been shown to suppress the growth of myeloid leukemia cells." (PMID 36230684, 2022).
myocardial infarction (1 paper, 2024). Gross necrosis of the myocardium, as a result of interruption of the blood supply to the area, as in coronary thrombosis. "Tyro3, the least studied TAM receptor in cardiovascular disease, appears to protect against fibrosis in post-myocardial infarction injury." (PMID 39684449, 2024).
myopia (1 paper, 2023). "Additionally, we identified 4 significant DEGs of myopia: KIAA1211, CALR3, DNASE2B, and CCDC178, and 2 common targets: AR and TYRO3 among DZP, myopia, DEG analysis, and WGCNA." (PMID 37747014, 2023).
opioid dependence (1 paper, 2025). "We observed elevated CSF levels of sTREM2, and, after normalization to water content, also increases in YKL‐40, IL‐8 and TYRO3 in the opioid dependence group." (PMID 40454659, 2025). "Normalization uncovered additional significant group differences, with YKL‐40, IL‐8, TYRO3 and P‐tau levels elevated in the opioid group, further indicating neuroimmune activation in opioid dependence." (PMID 40454659, 2025). "Taken together, our findings suggest that opioid dependence is associated with neuroimmune activation, evidenced by elevated markers of glial activation (sTREM2 and YKL‐40), increased IL‐8 and the activation of regulatory pathways involving TYRO3." (PMID 40454659, 2025). "The elevated levels of TYRO3 observed in the opioid dependence group may therefore reflect an adaptive response aimed at controlling ongoing inflammation." (PMID 40454659, 2025).
Oral ulcer (1 paper, 2020). Erosion of the mucous mebrane of the mouth with local excavation of the surface, resulting from the sloughing of inflammatory necrotic tissue. "It was interesting that the statistical analysis showed that patients with the presence of oral ulcers had higher levels of anti-Tyro3 IgG, and there was little known about the relationship between TAM autoantibodies and oral ulcers." (PMID 33224991, 2020). "Higher levels of anti-Tyro3 antibody were observed in patients with oral ulcers than patients without oral ulcers (p = 0.035)." (PMID 33224991, 2020).
osteoarthritis (1 paper, 2025). A noninflammatory degenerative joint disease occurring chiefly in older persons, characterized by degeneration of the articular cartilage, hypertrophy of bone at the margins and changes in the synovial membrane. "In osteoarthritis, impaired efferocytosis and elevated levels of apoptotic cells have been observed in synovial tissues, which have been linked to the deficiency of membrane-bound TAM receptors (Tyro3, AXL, and MERTK)." (PMID 40458640, 2025).
Osteopenia (1 paper, 2022). Osteopenia is a term to define bone density that is not normal but also not as low as osteoporosis. "Therefore, MERTK represents a novel target whose inhibition counteracts cancer-induced osteopenia through stimulation of osteoblast function, whereas TYRO3 represents a bone protective factor." (PMID 36509738, 2022).
osteoporosis (1 paper, 2022). A condition of reduced bone mass, with decreased cortical thickness and a decrease in the number and size of the trabeculae of cancellous bone (but normal chemical composition), resulting in increased fracture incidence. "Further work is warranted to dissect the regulation of the MERTK vs. TYRO3 pathway in osteoblasts in health and disease conditions, including osteoporosis." (PMID 36509738, 2022).
pheochromocytoma (1 paper, 2025). "Then, we constructed amino acid metabolism profiles by WGCNA and LASSO regression model for investigating the impact of amino acid metabolism on pheochromocytoma pathogenesis and immunity and identified six hub genes (DDC, SYT11, GCLM, PSMB7, TYRO3, and AGMAT)." (PMID 38526709, 2025).
rectal cancer (1 paper, 2023). A primary or metastatic malignant neoplasm that affects the rectum. "The results indicated that TYRO3 expression was positively associated with ENO1 expression in colon and rectal cancer tissues from TCGA database." (PMID 37116196, 2023).
renal cell carcinoma (1 paper, 2022). "TYRO3 is a key part of the tumor-associated macrophage (TAM) receptor-ligand complex, which are implicated in several hallmarks of cancer progression and involves in the acquisition of the resistance to sunitinib in renal cell carcinoma." (PMID 36159976, 2022).
renal failure (1 paper, 2013). "Patients with renal failure (n = 5) presented higher values of GAS6 (42.5 ± 4.0 ng/mL vs 31.2 ± 1.5 ng/mL; P = 0.023); MerTK (31.4 ± 7.3 ng/mL vs 20.1 ± 1.4 ng/mL; P = 0.024); and Tyro3 (4.6 ± 0.4 ng/mL vs 3.5 ± 0.2 ng/mL; P = 0.031)." (PMID 23497733, 2013).
retinal diseases (1 paper, 2020). "Investigating the pathways and mechanisms in which Tyro3 regulates RGC survival and morphology could inform new therapeutic approaches in retinal diseases." (PMID 32922258, 2020).
schwannoma (1 paper, 2018). A benign, usually encapsulated slow growing tumor composed of Schwann cells. "Similarly, TYRO3 protein levels were dramatically increased in primary human schwannoma cells relative to normal Schwann cells." (PMID 30501104, 2018).
Senile plaques (1 paper, 2012). Senile plaques are extracellular deposits of amyloid in the gray matter of the brain. "We observed that the APP processing mediated by BACE1 was inhibited by Tyro3 overexpression in vitro, and the number of senile plaques resulting from Aβ deposition was increased by Tyro3 gene knockdown in an AD mouse model." (PMID 22701746, 2012).
Sepsis (1 paper, 2021). Sepsis is defined as life-threatening organ dysfunction caused by a dysregulated host response to infection. "As growth arrest-specific gene 6 (Gas6)/Tyro3, Axl, MerTK (TAM) receptors signaling has shown immunomodulatory activity in sepsis, here we sought to determine whether Gas6 protein injection could mitigate MOF in a cecal slurry mouse model of sepsis." (PMID 33803290, 2021).
somatotropinomas (1 paper, 2025). "Among the genes included in this pathway, recent studies have suggested that FANCD2, SPTA1, TYRO3, and ZNF335 genes are emerging as key players in immune response and regulating tumorigenesis, even if their role has not been studied in TME of somatotropinomas." (PMID 40415137, 2025).
Thromboembolism (1 paper, 2018). The formation of a blood clot inside a blood vessel that subsequently travels through the blood stream from the site where it formed to another location in the body, generally leading to vascular occlusion at the distant site. "In Tyro3−/− mice, thrombus size was reduced by 90% compared to wild-type mice after ligation and injection of tissue thromboplastin in the inferior vena cava and only 25% of Tyro3−/− mice had a fatal thromboembolism in response to treatment with collagen and epinephrine compared to 80% of wild-type." (PMID 30501104, 2018).
thymic carcinoma (1 paper, 2022). Thymic carcinoma (TC) is a type of thymic epithelial neoplasm characterized by a high malignant potential. "TYRO3 may thus be both a novel biomarker of sunitinib resistance and a potential therapeutic target in advanced thymomas and thymic carcinomas." (PMID 36230684, 2022). "TYRO3 could serve both as a biomarker of sunitinib resistance and a potential therapeutic target that could help to tailor treatment decisions and to overcome therapy resistance in advanced thymomas and thymic carcinomas." (PMID 36230684, 2022).
thymoma (1 paper, 2022). A neoplasm arising from the epithelial cells of the thymus. "Bioinformatic prediction and further experimental analysis of activated upstream kinases identified TYRO3 as a potent mediator of sunitinib resistance, specifically in metastatic thymomas." (PMID 36230684, 2022).
urothelial carcinoma (1 paper, 2022). A malignant neoplasm derived from the transitional epithelium of the urinary tract (urinary bladder, ureter, urethra, or renal pelvis). "TYRO3, which has been recently identified as a potential therapeutic target in urothelial carcinoma, has been identified as one of the seven commonly secreted proteins from GCT cell lines." (PMID 35811571, 2022).
tumor (137 papers, 2012 to 2026). "TYRO3 is associated with HCC tumor progression and sorafenib resistance, with increased sorafenib sensitivity observed following TYRO3 knockdown in vitro." (PMID 40424447, 2025). "TYRO3 activation induces the polarisation of tumour-associated macrophages towards an anti-inflammatory M2 phenotype." (PMID 40088262, 2025). "One major issue is the broad expression of TAM receptors (Tyro3, Axl, MerTK) across both tumor and normal tissues, which increases the risk of off-tumor effects such as impaired clearance of apoptotic cells and autoimmune-like toxicities." (PMID 40821795, 2025). "TYRO3 is a tyrosine-protein kinase receptor that has also been implicated in tumor resistance to PD-1 inhibition." (PMID 38738146, 2024). "In contrast to other multi–tyrosine kinase inhibitors, cabozantinib targets VEGFR-1–3 as well as MET and the tumor-associated macrophage (TAM) family (TYRO3, AXL, and MER) of receptor kinases." (PMID 36982920, 2023). "The TAM (Axl, Mer, and Tyro3) family is implicated in the survival and chemoresistance of tumours and has emerged as a potential therapeutic target." (PMID 32972253, 2020). "This inhibition of tumour growth was associated with significantly lower TYRO3 mRNA levels on RT-qPCR." (PMID 30765874, 2019). "The treatment of two tumour protein samples with peptide N-glycanase F (PNGaseF), an enzyme that removes N-linked glycans, shifted the TYRO3 band to the expected theoretical molecular weight of 96 kDa, confirming the N-glycosylation of this receptor." (PMID 30765874, 2019). "The TAM receptors (Tyro3, Axl and MerTK) are promising therapeutic targets on tumor-associated macrophages." (PMID 31088471, 2019). "Consistent with the known roles for TYRO3 in tumor cell survival, TYRO3 has been implicated as a mediator of resistance to both traditional cytotoxic chemotherapies and molecularly-targeted agents." (PMID 30501104, 2018). "ERBB2, ERBB3 and SYK were functionally more active overall in tumors and TYRO3 was more active in paired tumor samples and also mutated on kinase gene sequencing." (PMID 28423512, 2017). "Finally, growth inhibition upon TYRO3 depletion relies on cell cycle inhibition and apoptosis associated with induction of tumour-suppressive signals." (PMID 30765874, 2019). "PI3K/AKT signaling has also been implicated downstream of TYRO3 in tumor cells." (PMID 30501104, 2018). "While Axl levels are significantly high in quiescent cells, Tyro3 has been associated with rapid tumor growth, suggesting that a balance between the expression of Axl and Tyro3 might influence the switch of PCa cells from a dormant to proliferative state and vice versa." (PMID 33747899, 2020). "Importantly, clinicopathological analysis showed that increased TYRO3 expression was significantly associated with large tumor size, clinical metastasis, and poor prognosis, suggesting that TYRO3 overexpression was strongly suggestive of the proliferative and metastatic state in patients with GC." (PMID 32018224, 2020). "Further studies have found that, due to its unique biological activity in regulating bone homeostasis, TYRO3 also plays a role in the development of tumour bone metastases." (PMID 40088262, 2025). "TYRO3 reduces the therapeutic effects of anti-PD-1/PD-L1 by inhibiting ferroptosis in tumor tissues." (PMID 40959280, 2025). "Inhibition of TYRO3 can promote tumor cell ferroptosis, enhance the sensitivity of resistant tumors to anti-PD-1 therapy, and drive the development of a pro-tumor microenvironment by reducing the M1/M2 macrophage ratio." (PMID 40260246, 2025). "TYRO3+NK cells exhibited significantly higher cytotoxicity compared to TYRO3−NK cells, thereby showcasing enhanced anti-tumor response." (PMID 41181711, 2025).